FHL3 (four and a half LIM domains 3)
Description:
Recruited by SOX15 to FOXK1 promoters where it acts as a transcriptional coactivator of FOXK1.
Synonyms: SLIM2
Tractability: PROTAC: ubiquitination databases record sites on it; its protein half-life has been measured.
Gene: Protein-coding gene on chromosome 1 (37,994,394 to 38,006,380, reverse strand). Ensembl gene ENSG00000183386.
Subcellular location: Nucleus; Cytoplasm
Subcellular location (Human Protein Atlas): Nucleoplasm
Gene Ontology:
Molecular function: protein binding; actin binding; transcription coregulator activity
Biological process: actin cytoskeleton organization; muscle organ development
Cellular component: focal adhesion; cytoplasm; nucleus; stress fiber; Z disc
Genetic constraint (gnomAD): Loss-of-function variants: 21 observed, 36.23 expected, observed/expected ratio (o/e) 0.58, 90% interval 0.41 to 0.83. The upper end of that interval is the gene's LOEUF score, 0.83, which puts it in group 3 of 6, group 1 being the genes least tolerant of losing a copy. Missense variants: 333 observed, 393.63 expected, observed/expected ratio (o/e) 0.85, 90% interval 0.77 to 0.93. Synonymous variants: 137 observed, 152.19 expected, observed/expected ratio (o/e) 0.9, 90% interval 0.78 to 1.04.
Homologues: Orthologues: chimpanzee FHL3 (99% identical), macaque FHL3 (99% identical), rabbit FHL3 (98% identical), mouse Fhl3 (98% identical), pig FHL3 (98% identical), dog FHL3 (97% identical), guinea pig FHL3 (96% identical), rat Fhl3 (85% identical), tropical clawed frog fhl3 (70% identical), zebrafish fhl3a (69% identical), zebrafish fhl3b (64% identical), Caenorhabditis elegans lim-9 (50% identical). Paralogues in human: FHL2 (53% identical), FHL5 (47% identical).
Diseases named in the same sentence as FHL3 in open-access papers:
FHL3 is named in the same sentence as 35 diseases in open-access papers, as found by Europe PMC text mining. Sharing a sentence is not in itself a finding about the gene and the disease. The quoted sentences say what the papers report.
gastric cancer (5 papers, 2021 to 2025). A primary or metastatic malignant neoplasm involving the stomach. "FHL3 is overexpressed in many tumor types such as gastric cancer and glioma stem cells, while being downregulated in breast cancer." (PMID 35686099, 2022). "FHL3 competitively bonded the ubiquitin complex with Slug, resulting in the up-regulation of Slug and leading to metastasis of gastric cancer." (PMID 34150617, 2021). "Colony formation assay and live and death staining assay were performed to detect the effect of FHL3 knockdown when gastric cancer cell received OHP therapy." (PMID 34150617, 2021). "mRNA and protein level of FHL3 were significantly up-regulated in gastric cancer tissues when compared with adjacent tissue." (PMID 34150617, 2021). "FHL3 has a tumor-promoting effect in gastric cancer and non‐small cell lung cancer." (PMID 35686099, 2022). "The function of FHL3 in NSCLC appears to be similar to gastric cancer." (PMID 35686099, 2022). "In addition, FHL3 shows high expression in gastric cancer, glioma stem cells, pancreatic ductal adenocarcinoma, non‐small cell lung cancer T-cell leukemia, A673 neuroepithelioma cells, and tumor angiogenesis." (PMID 35686099, 2022). "Therefore, FHL3 was likely to regulate gastric cancer metastasis through TGFβ/Smad-independent pathway." (PMID 34150617, 2021). "Then, we validated the role of FHL3 in metastasis of gastric cancer cells in vivo." (PMID 34150617, 2021). "Previous studies have reported that FHL3 knockdown significantly inhibits the phosphorylation of the MAPK pathway components, including p38, ERK1/2, and JNK in gastric cancer cell lines, with FHL3 preventing substrate protein ubiquitination and degradation." (PMID 40225558, 2025). "In this study, we explored the potential relationship between FHL3 and EMT/chemotherapy resistance in gastric cancer." (PMID 34150617, 2021). "However, the role of FHL3 in gastric cancer still remains unclear." (PMID 34150617, 2021). "We detected the FHL3 expression level in a normal gastric cell line (GES-1) and several gastric cancer cell lines (SGC, HGC, AGS and N87)." (PMID 34150617, 2021). "As of now, no research article has revealed the role of FHL3 in gastric cancer, especially the regulatory mechanism of FHL3 in chemoresistance and metastasis." (PMID 34150617, 2021). "Furthermore, FHL3 could promote EMT and chemotherapy resistance via up-regulating Slug and activating TGF-β/Smad-independent pathways, thus leading to metastasis of gastric cancer." (PMID 36901953, 2023).
glioma (5 papers, 2015 to 2025). A benign or malignant brain and spinal cord tumor that arises from glial cells (astrocytes, oligodendrocytes, ependymal cells). "Inhibition of PCBP2 enhanced FHL3 expression by stabilizing its mRNA, leading to the increased expression of P21 in glioma cells." (PMID 35686099, 2022). "Conversely, FHL3 acts as a tumor suppressor in glioma stem cells and pancreatic ductal adenocarcinoma, which induces cell-cycle arrest." (PMID 35686099, 2022). "In glioma stem cells, FHL3 inhibits the Smad2/3-SOX4-SOX2 axis." (PMID 35686099, 2022). "However, it was confirmed that SOX4 can also promote tumor progression by interacting with the transcription factors Smad2/3 as well as dephosphorylating PPM1A and FHL3, which decreases the self-renewal capacity of glioma stem cells." (PMID 35686099, 2022). "In the current study, we sought to determine whether FHL3 is involved in Ang-regulated glioma progression." (PMID 25659096, 2015).
hepatocellular carcinoma (3 papers, 2014 to 2025). A malignant tumor that arises from hepatocytes. "FHL3 was found to be downregulated in hepatocellular carcinoma and breast cancer, indicating that it plays a role in inhibiting tumor growth." (PMID 35686099, 2022). "It has been demonstrated that FHL3 physically and functionally interact with Smad2, Smad3, and Smad4, important regulators of cancer development and progression, and inhibit human hepatoma cell growth in vitro and in vivo." (PMID 24690879, 2014). "Recently, it has been shown that FHL1, FHL2, and FHL3 physically and functionally interact with Smad2, Smad3, and Smad4, important regulators of cancer development and progression, and inhibit human hepatoma cell growth in vitro and in vivo." (PMID 24690879, 2014). "Given that the role of FHL3 in human hepatoma cell, we sought to determine whether MT-1X could play a role in the regulation of FHL3-mediated human hepatoma cell growth." (PMID 24690879, 2014).
astrocytoma (2 papers, 2015 to 2023). "In conclusion, the present study established a link between Ang and FHL3 proteins and identifies a new pathway for regulating astrocytoma progression." (PMID 25659096, 2015). "In our study, the expression of FHL3 negatively correlated to the malignant grades of astrocytomas." (PMID 25659096, 2015).
breast carcinoma (2 papers, 2014 to 2022). "Overexpression and silencing demonstrated that FHL3 can inhibit the growth of breast cancer cells by inducing cell cycle arrest in the G1 and G2/M phases." (PMID 35686099, 2022). "In addition, FHL3 is involved in the development and progression of breast cancer by suppressing breast cancer cell growth and inducing cell-cycle arrest." (PMID 24690879, 2014). "By establishing a link between MT-1X and FHL3, our findings suggest that FHL3 may be involved in the regulating the function of MT-1X in breast cancer cell as a MT-1X interactor." (PMID 24690879, 2014). "Similarly, FHL3 was found to be downregulated in breast cancer cells compared with normal cells." (PMID 35686099, 2022). "Based on these findings, it can be hypothesized that the regulation of P21 expression in breast cancer cells may be influenced by the interactions of FHL3 with Smad proteins, although it cannot be ruled out that FHL3 may affect P21 expression via other protein partners." (PMID 35686099, 2022).
pancreatic cancer (2 papers, 2020 to 2021). "FHL3 promotes metastasis by upregulating the expression of EMT associated transcription factors in pancreatic cancer cell lines." (PMID 31935687, 2020). "Then, we explored the effects of FHL3 on the EMT process and the underlying mechanisms of FHL3 in pancreatic cancer (PC) cell lines." (PMID 31935687, 2020). "In our previous study, FHL3 also acts as a regulator in ubiquitin degradation process of EMT-TFs through Akt/GSK3β/ubiquitin pathway in pancreatic cancer." (PMID 34150617, 2021). "Our previous study has revealed Four and a Half LIM Domains 3 (FHL3) plays as a binding partner of Glycogen Synthase Kinase 3 Beta (GSK3β), promoted tumor metastasis in pancreatic cancer." (PMID 34150617, 2021). "In our previous study, we have found that FHL3 participates in Akt/GSK3β pathway-mediated ubiquitination degradation of EMT-TFs, and the E3 ligase RNF146 was firstly reported to interact with FHL3 in pancreatic cancer." (PMID 34150617, 2021). "We found weaker metastatic ability in pancreatic cancer cells (PANC1_KD1 and BXPC3_KD1 cells), both in vitro and in vivo experiments, after FHL3 knockdown (Figure 6F1-2)." (PMID 31935687, 2020). "Furthermore, based on our previous study that FHL3 regulated the Akt/GSK3β/ubiquitin-Snail1|Twist1 pathway to stabilize the EMT-TFs to promote EMT process in pancreatic cancer, we explored the role of FHL3 in the regulation of ubiquitin-mediated EMT." (PMID 34150617, 2021). "Then, we validated the role of FHL3 in growth and migration of pancreatic cancer cells in vivo." (PMID 31935687, 2020).
atherosclerosis (1 paper, 2015). A disease characterized by the build-up of fatty material and calcium deposition in the arterial wall resulting in partial or complete occlusion of the arterial lumen. "In a mouse model of atherosclerosis, FHL3 was demonstrated to have anti-apoptotic effects in endothelial cells, through up-regulation of Bcl-2 via the PI3K pathway." (PMID 25860936, 2015).
bladder cancer (1 paper, 2019). "Among other Pi-specific hub genes: ADRBK1 is known to be involved in neuroinflammation and multiple sclerosis; FHL3 is involved in regulating integrin-mediated cytoskeletal events; PPP2CB is known to be involved in bladder cancer." (PMID 31536525, 2019).
Chediak-Higashi syndrome (1 paper, 2023). ChC)diak-Higashi syndrome (CHS) is a rare severe genetic disorder generally characterized by partial oculocutaneous albinism (OCA), severe immunodeficiency, mild bleeding, neurological dysfunction and lymphoproliferative disorder. "Since then, the study of familial cases allowed the recognition of genetic alterations directly affecting proteins involved in cytotoxic activity, such as Munc13-4 (FHL-3), Syntaxin 11 (FHL-4), Munc18-2 (FHL-5), RAB27A (Griscelli Syndrome type 2, GS2), LYST (Chediak-Higashi Syndrome, CHS)." (PMID 37426667, 2023).
Emery-Dreifuss muscular dystrophy (1 paper, 2018). Emery-Dreifuss muscular dystrophy (EDMD) is characterized by muscular weakness and atrophy, with early joint contractures and cardiomyopathy. "FHL3 is closely related to FHL1 that is directly linked to Emery-Dreifuss muscular dystrophy." (PMID 29912636, 2018).
gastric tumor (1 paper, 2021). "To confirm this observation, we examined the FHL3 level in clinical gastric tumor samples." (PMID 34150617, 2021). "In line with this conclusion, FHL3 protein level was also significantly elevated in GC by proteogenomic analysis of Beijing dataset which contained 58 paired gastric tumor samples and non-tumor adjacent tissues (PXD011821, P < 0.001)." (PMID 34150617, 2021).
Griscelli syndrome type 2 (1 paper, 2023). Griscelli syndrome type 2 (GS2) is a rare, inherited condition that affects the skin, hair, and immune system. "The following FHL subtypes have been described: FHL-2 due to mutations in PRF1, FHL-3 (UNC13D), FHL-4 (STX11), FHL-5 (STXBP2), Griscelli Syndrome type 2 (RAB27A) and Chediack-Higashi syndrome (LYST)." (PMID 37426667, 2023).
laminopathy (1 paper, 2018). A rare genetic disorder caused by mutations in genes encoding proteins of the nuclear lamina. "The finding of predicted novel alternative splicing events or novel antisense transcription in both other laminopathy-linked genes encoding nesprin 2 and Lap2 and other muscular dystrophy-linked genes such as FHL3 underscore the need for this type of analysis." (PMID 29912636, 2018).
lymph node metastasis (1 paper, 2021). "The multivariate Cox proportional hazards model showed lymph node metastasis (Hazard ratio = 1.47, 95% CI: 1.09–1.98, P = .011) and FHL3 (Hazard ratio = 2.06, 95% CI: 1.23–3.42, P = 0.005) were the independent risk factors of overall survival in GC." (PMID 34150617, 2021). "In univariate analysis, lymph node metastasis (Hazard ratio = 1.43, 95% CI: 1.15–1.78, P = 0.001) and FHL3 (Hazard ratio = 2.29, 95% CI: 1.45–3.63, P < 0.001) were identified as risk factors of disease progression in GC." (PMID 34150617, 2021).
Obesity (1 paper, 2021). Accumulation of substantial excess body fat. "Four genes were identified to be significantly affected by aging, obesity, and exercise (Serpinh1, Vwa1, Mest, and Fhl3)." (PMID 33661096, 2021).
prostate carcinoma (1 paper, 2023). A carcinoma that arises from epithelial cells of the prostate gland. "To further understand how Curcusone C exerted activities, we validated the mechanism of anti-prostate cancer of Curcusone C. Four and a half LIM domain protein 3 (FHL3) was associated with inhibition of cell apoptosis." (PMID 37814239, 2023). "Our results indicated that Curcusone C can inhibit the proliferation and metastasis in prostate cancer cells through activating the expression of FHL3 and repressing PCBP2 through suppressing TGF/Smad signaling pathway, and the result was similar to studies of Mao and colleagues." (PMID 37814239, 2023).
tumor (11 papers, 2014 to 2025). "Chi-square test revealed that high FHL3 expression was associated with clinical features such as larger tumor volume, vascular invasion, and higher tumor grade." (PMID 41184244, 2025). "In the liver orthotopic xenotransplantation assay, simultaneous knockdown of KRAS significantly reduced the stronger fluorescence intensity and larger tumor volume caused by FHL3 than did FHL3 overexpression alone." (PMID 41184244, 2025). "Western blot (WB) and immunohistochemical (IHC) showed high protein levels of FHL3 in tumor tissues and the expression of FHL3 was associated with poorer prognosis." (PMID 41184244, 2025). "According to the IHC staining result, up-regulated FHL3 expression was positively associated with the tumor TNM stage." (PMID 34150617, 2021). "The risk score of each patient was calculated using the following formula based on their regression coefficient of the expression levels of these 3 markers: risk score = 0.003 × Hscore of FHL3 in tumor -0.006× Hscore of GGA1 in tumor +0.004× Hscore of TGFBI in stromal." (PMID 37258779, 2023). "FHL3 may promote EMT-mediated tumor invasion and EMT-associated chemotherapy resistance in GC progression through various pathways." (PMID 34150617, 2021). "FHL3 knockdown inhibited the tumor-promoting effect of YAP and significantly delayed the tumorigenesis and progression caused by YAP." (PMID 41184244, 2025). "The results revealed that FHL3 was expressed mainly in the nucleus, which was consistent with previous results, and the expression of FHL3 in tumor tissues was greater than that in adjacent tissues." (PMID 41184244, 2025). "The target gene of Hippo-YAP pathway, Four and a half LIM domain protein 3 (FHL3), was screened by spontaneous hydrodynamic tumor model with YAP participation and two publicly HCC microarray sets." (PMID 41184244, 2025). "To investigate the potential biological function of FHL3 in tumor cells, we first detected FHL3 expression levels in seven HCC cell lines." (PMID 41184244, 2025). "On the other hand, FHL3 can act as a tumor suppressor and affect the expression of downstream genes." (PMID 38789729, 2024). "On the one hand, FHL3 can play a role as a cancer protein in some cancers, promoting tumor progression through phosphorylation." (PMID 38789729, 2024). "Conversely, the downregulation of FHL3 can promote the expression of E-cadherin and reduce the migration ability of tumor cells." (PMID 35686099, 2022). "On the one hand, FHL3 can function as a tumor suppressor and influence the expression of downstream genes." (PMID 35686099, 2022). "In recent years, there has been increasing evidence of a relation between FHLs and tumor biology, since FHL3 is often overexpressed or downregulated in different cancers." (PMID 35686099, 2022). "On the other hand, FHL3 can also play a role as an oncoprotein in some cancers to promote tumor progression via phosphorylation." (PMID 35686099, 2022). "In subcutaneous tumor model, our study found that FHL3 knockdown reduced the tumor growth ~25% of tumor volume and ~25% of tumor weight." (PMID 34150617, 2021). "The mechanisms of how FHL3 regulates tumor chemotherapy resistance and metastasis were unclear in GC." (PMID 34150617, 2021). "Collectively, FHL3 knockdown significantly enhanced the OHP-induced tumor growth inhibition rate about one-fold as compared with the single OHP treatment group (P < 0.05)." (PMID 34150617, 2021). "Consistently, the expression of FHL3 was dramatically up-regulated in GC tissues when compared with adjacent tissues in both 120 matched paraffin-embedded tumor tissue sections and 16 paired fresh frozen tissue (P < 0.05)." (PMID 34150617, 2021). "In agreement with previous report, FHL3 expression was decreased in the tumor tissues and FHL3 inhibited U87MG cell proliferation as evaluated by MTT assay." (PMID 25659096, 2015).